IGKV1-17 (immunoglobulin kappa variable 1-17)
Description:
V region of the variable domain of immunoglobulin light chains that participates in the antigen recognition. Immunoglobulins, also known as antibodies, are membrane-bound or secreted glycoproteins produced by B lymphocytes. In the recognition phase of humoral immunity, the membrane-bound immunoglobulins serve as receptors which, upon binding of a specific antigen, trigger the clonal expansion and differentiation of B lymphocytes into immunoglobulins-secreting plasma cells. Secreted immunoglobulins mediate the effector phase of humoral immunity, which results in the elimination of bound antigens. The antigen binding site is formed by the variable domain of one heavy chain, together with that of its associated light chain. Thus, each immunoglobulin has two antigen binding sites with remarkable affinity for a particular antigen. The variable domains are assembled by a process called V-(D)-J rearrangement and can then be subjected to somatic hypermutations which, after exposure to antigen and selection, allow affinity maturation for a particular antigen.
Synonyms: IGKV117; A30
Tractability: Antibody: its Gene Ontology location is reachable by antibodies, with high confidence; UniProt places it where antibodies can reach, with medium confidence; UniProt predicts a signal peptide or a membrane-spanning region.
Gene: Immunoglobulin variable (V) gene on chromosome 2 (89,117,342 to 89,117,844, reverse strand). Ensembl gene ENSG00000240382.
Subcellular location: Secreted; Cell membrane
Pathways (Reactome):
Immune System: Antigen activates B Cell Receptor (BCR) leading to generation of second messengers; CD22 mediated BCR regulation; Classical antibody-mediated complement activation; FCERI mediated Ca+2 mobilization; FCERI mediated MAPK activation; FCERI mediated NF-kB activation; FCGR activation; Fc epsilon receptor (FCERI) signaling; Immunoregulatory interactions between a Lymphoid and a non-Lymphoid cell; Initial triggering of complement; Regulation of Complement cascade; Regulation of actin dynamics for phagocytic cup formation; Role of LAT2/NTAL/LAB on calcium mobilization; Role of phospholipids in phagocytosis
Disease: FCGR3A-mediated IL10 synthesis; FCGR3A-mediated phagocytosis; Potential therapeutics for SARS
Hemostasis: Cell surface interactions at the vascular wall
Vesicle-mediated transport: Scavenging of heme from plasma
Gene Ontology:
Molecular function: antigen binding
Biological process: immune response
Cellular component: blood microparticle; extracellular exosome; extracellular region; immunoglobulin complex; plasma membrane
Homologues: Orthologues: mouse Igkv15-103 (74% identical). Paralogues in human: IGKV1-6 (94% identical), IGKV1D-17 (91% identical), IGKV1-12 (91% identical), IGKV1-16 (91% identical), IGKV1-9 (91% identical), IGKV1D-16 (91% identical), IGKV1D-12 (90% identical), IGKV1-39 (89% identical), IGKV1D-13 (89% identical), IGKV1D-39 (89% identical), IGKV1-27 (87% identical), IGKV1-5 (87% identical), and 81 more.
Diseases named in the same sentence as IGKV1-17 in open-access papers:
IGKV1-17 is named in the same sentence as 1 disease in open-access papers, as found by Europe PMC text mining. Sharing a sentence is not in itself a finding about the gene and the disease. The quoted sentences say what the papers report.
nephritis (1 paper, 2020). Inflammation of renal tissue. "IGKV1-17 gene was reported to be rarely expressed by normal cells and play a critical role in the development of SLE-nephritis." (PMID 33072067, 2020).